NFRKB (nuclear factor related to kappaB binding protein)
Description:
Binds to the DNA consensus sequence 5'-GGGGAATCTCC-3'. Putative regulatory component of the chromatin remodeling INO80 complex which is involved in transcriptional regulation, DNA replication and probably DNA repair. Modulates the deubiquitinase activity of UCHL5 in the INO80 complex.
Synonyms: INO80G; DKFZp547B2013
Tractability: PROTAC: UniProt records ubiquitination sites on it; ubiquitination databases record sites on it; its protein half-life has been measured.
Gene: Protein-coding gene on chromosome 11 (129,863,636 to 129,895,590, reverse strand). Ensembl gene ENSG00000170322.
Subcellular location: Nucleus
Subcellular location (Human Protein Atlas): Nucleoplasm
Pathways (Reactome):
DNA Repair: DNA Damage Recognition in GG-NER
Metabolism of proteins: UCH proteinases
Gene Ontology:
Molecular function: protease binding; protein binding
Biological process: chromatin remodeling; positive regulation of DNA-templated transcription; regulation of cell cycle; regulation of chromosome organization; regulation of DNA replication; regulation of DNA strand elongation; positive regulation of DNA repair; positive regulation of telomere maintenance in response to DNA damage; regulation of DNA metabolic process; regulation of DNA repair; regulation of embryonic development; telomere maintenance
Cellular component: Ino80 complex; nucleoplasm; nucleus
Genetic constraint (gnomAD): Loss-of-function variants: 62 observed, 140.95 expected, observed/expected ratio (o/e) 0.44, 90% interval 0.36 to 0.54. The upper end of that interval is the gene's LOEUF score, 0.54, which puts it in group 2 of 6, group 1 being the genes least tolerant of losing a copy. Missense variants: 1,545 observed, 1,725.5 expected, observed/expected ratio (o/e) 0.9, 90% interval 0.86 to 0.93. Synonymous variants: 678 observed, 663.84 expected, observed/expected ratio (o/e) 1.02, 90% interval 0.96 to 1.09.
Homologues: Orthologues: chimpanzee NFRKB (99% identical), macaque NFRKB (99% identical), dog NFRKB (97% identical), rabbit NFRKB (96% identical), pig NFRKB (95% identical), guinea pig NFRKB (95% identical), mouse Nfrkb (94% identical), rat Nfrkb (94% identical), tropical clawed frog nfrkb (67% identical), zebrafish nfrkb (60% identical), Drosophila melanogaster CG11970 (28% identical).
Diseases named in the same sentence as NFRKB in open-access papers:
NFRKB is named in the same sentence as 18 diseases in open-access papers, as found by Europe PMC text mining. Sharing a sentence is not in itself a finding about the gene and the disease. The quoted sentences say what the papers report.
gastric cancer (4 papers, 2020 to 2022). A primary or metastatic malignant neoplasm involving the stomach. "lncRNA DRAIC also hindered cell metastasis through its interaction with UCHL5 and repression of NFRKB deubiquitination in gastric cancer." (PMID 35992823, 2022). "DRAIC/NFRKB reduces gastric cancer metastasis by degrading the NFRKB protein." (PMID 33050646, 2020). "For example, it was found in gastric cancer cells that DRAIC can promote the degradation of NFRKB and inhibit the proliferation and metastasis of gastric cancer cells by blocking NFRKB de-ubiquitination mediated by UCHL5." (PMID 34306024, 2021). "In gastric cancer, lncRNA DRAIC has also been indicated to inhibit the proliferation of SGC-7901, HGC-27, and MKN45 cells by binding to UCHL5 and accelerating the ubiquitination of NFRKB." (PMID 35992823, 2022). "Furthermore, we observed that the expression of DRAIC decreased with the progression of gastric cancer, while the low expression of DRAIC and high expression of NFRKB were extremely adverse for the prognosis of GC patients." (PMID 32351584, 2020).
asthma (1 paper, 2019). "Moreover, five additional genes (KAT2A, HIST1H1C, NFRKB, C14orf178 and ZNF213-AS1) were suggestively associated with asthma (P < 0.0001) from the regular Omnibus-Fisher test." (PMID 31063461, 2019).
Immunodeficiency (1 paper, 2021). Failure of the immune system to protect the body adequately from infection, due to the absence or insufficiency of some component process or substance. "The expression of the THYN1 gene in these immune cells leads us to propose its implication in the immunodeficiency of JBS patients, along with FLI-1, ETS1, NFRKB and JAM3." (PMID 34440371, 2021). "ETS1, NFRKB, JAM3 and THYN1 genes could also play a role in the presence of immunodeficiency." (PMID 34440371, 2021).
Infertility (1 paper, 2021). "Other major DEPs, including RNASEH2C, TAPBPL, TUBB8, NFRKB, MASTL, and MYLK, have never been reported to be associated with infertility, metabolic disorders, or hormone imbalances." (PMID 34016141, 2021).
membranous nephropathy (1 paper, 2012). "The expression of NFRKB in active membranous nephropathy (MN) was not significantly different from normal controls, which suggests that the upregulation of NFRKB is apparently not a consequence of nephrotic syndrome." (PMID 22291976, 2012).
papillary thyroid cancer (1 paper, 2021). "Of note, the NFRKB variant rs200192480 (c.C2113T, p.P705S) was reported as segregating in one family with five members affected by papillary thyroid cancer." (PMID 34067022, 2021).
cancer (3 papers, 2020 to 2022). A tumor composed of atypical neoplastic, often pleomorphic cells that invade other tissues. "It was found that oeNFRKB could alleviate the anti-cancer effect induced by DRAIC in HGC-27 and MKN45 cells, suggesting that DRAIC plays an anti-cancer role by suppressing NFRKB." (PMID 32351584, 2020). "Lower levels of SIGIRR and of TOLLIP, NFRKB, TNFRSF1A, and CD14 and of two distinct MAP kinases were detected in all the cancer cell lines analyzed; on the contrary, IRAK1 and HSPD1 mRNAs were upregulated in all the tumor cells." (PMID 35814450, 2022). "Considering the potential value of UCHL5/NFRKB in cancer, we analyzed the expression of UCHL5 and NFRKB in GC through the TCGA database and qPCR, whose results demonstrated that UCHL5 and NFRKB were up-regulated in GC." (PMID 32351584, 2020). "Based on the differential expression of DRAIC in GC and NC tissues and its potential role in several malignant tumors, we decided to explore the relationship between DRAIC/NFRKB and malignant phenotype of GC cells." (PMID 32351584, 2020).
tumor (2 papers, 2010 to 2022). "Of these, 83 were heterozygous novel SNPS, 3 were homozygous in the tumor only, presumably due to LOH, and 3 in NKX6-2, CDH8, and NFRKB were heterozygous point mutations." (PMID 20485525, 2010).
NFRKB also shares sentences with these, for which no sentence is quoted: Cirrhosis (1 paper); heart defects (1); Jacobsen syndrome (1); lung carcinoma (1); melanoma (1); metabolic disorders (1); minimal change nephrotic syndrome (1); nephrotic syndrome (1); neurodegenerative disease (1); Thrombocytopenia (1).